ERBB2 (erb-b2 receptor tyrosine kinase 2)
Diseases named in the same sentence as ERBB2 in open-access papers (continued):
Sharing a sentence is not in itself a finding about the gene and the disease.
invasive breast carcinoma (continued). "This cross-sectional study assesses the proportion of female patients with invasive breast cancer who have no record of testing for estrogen receptor, progesterone receptor, or ERBB2 status." (PMID 37615986, 2023). "Furthermore, we also detected the mRNA expression of ER, PR, and Her2 (ERBB2) in IBT and invasive breast cancer." (PMID 35992864, 2022). "ILC are characterized by a proliferation of non-cohesive cancer cells and usually display low tumor grade, high hormone receptors expression and a lower rate of ERBB2 amplification than invasive breast carcinomas of non-specific type." (PMID 27602491, 2016). "Persistent transactivation of EGFR and ErbB2/Her2 by the thrombin-cleaved PAR-1 pathway has been demonstrated in invasive breast carcinoma, but not in normal mammary epithelial cells." (PMID 26573921, 2015). "It is estimated that about 70%–80% of ErbB2 positive invasive breast cancers are either initially non-responsive or develop resistance to trastuzumab." (PMID 24709902, 2014). "TNBC, accounting for approximately 15% of all invasive breast cancers, is a rising burden globally; although the cutoffs used to define “positive” vs. “negative” expression of steroid hormone receptors and ERBB2 amplification/overexpression have changed over time." (PMID 34888495, 2021). "All patients included were diagnosed with stage I to stage III hormone receptor–positive, human epidermal growth factor receptor-2 (ERBB2; formerly HER2)–negative invasive breast cancer and underwent AHT without chemotherapy." (PMID 35166783, 2022). "The PS-weighted hazard ratio (HR) for invasive breast cancer-free survival comparing the EET with the no EET group was 0.68 (95% CI, 0.32-1.45) in luminal A-like, 0.63 (95% CI, 0.40-1.00) in luminal B-like/ERBB2-negative, and 0.62 (95% CI, 0.21-1.87) in ERBB2-positive subgroups." (PMID 42081244, 2026).
metastatic disease (786 papers, 1990 to 2026). "A notable finding of our study was the high degree of ERBB2 mutational discordance between patient-matched primary and metastatic tumor pairs and the urothelial cancer organoid models and the tumors from which they were derived." (PMID 41422272, 2025). "Although the absolute number of ERBB2 mutations was small, more were detected in metastatic tumor tissues and were significantly associated with shorter PFS." (PMID 36029565, 2022). "In our study, ERBB2 mutations were detected in 7 patients including 2 (6.1%) in primary tumor tissues, 2 (13.3%) in metastatic tumor tissues, and 3 (5.8%) by ctDNA analysis." (PMID 36029565, 2022). "These alterations included genetic loss of the RAS-GAP NF1 (8% of metastatic tumors) and activating mutations in ERBB2 (7% of metastatic tumors)." (PMID 34795269, 2021). "For example, EGFR, epidermal growth factor receptor, was overexpressed in the majority of clear-cell renal cell carcinoma and co-overexpression of EGFR and erbB-2 gene was associated with metastatic disease." (PMID 34335688, 2021). "Copy number gains are activating for oncogenes such as ERBB2 (identified in 2 of 10 metastatic tumor specimens analyzed) because they cause corresponding aberrant overexpression of gene transcripts." (PMID 25970776, 2015). "In medulloblastoma, ErbB2 overexpression upregulates prometastatic genes, increases the migration of medulloblastoma cells, and has been associated with advanced metastatic disease and poor clinical outcome 2,9,10." (PMID 25052069, 2014). "In medulloblastoma, which is thought to arise from cerebellar granule cell precursors, ErbB2 overexpression has been associated with advanced metastatic disease and poor clinical outcome." (PMID 25052069, 2014). "Discordance of ERBB2 mutational status between primary and metastatic disease sites is common in patients with urothelial cancer as is discordance of ERBB2 mutational status between patient-derived organoid/xenograft models and the tumors from which they were derived." (PMID 41422272, 2025). "Furthermore, identifying additional mutations, such as those in NF1 and ERBB2, highlights the genetic diversity and adaptability of metastatic tumors under selective pressure from endocrine therapies." (PMID 40075655, 2025). "Notably, consistent with the frequent ERBB2 mutational discordance between primary and metastatic tumor samples, three patients in our real-world cohort had discordance of ERBB2 mutational status between cfDNA and archival tumor tissue." (PMID 41422272, 2025). "For 30 ERBB2 altered patients in the cohort, tumor genomic profiling data was available for both primary and metastatic tumor sites." (PMID 41422272, 2025). "The report also illustrates how clonal evolution, such as acquired ERBB2 amplification, can occur in metastatic disease and influence treatment decisions." (PMID 41149070, 2025). "ERBB2 alterations were frequently discordant (12/30, 40%) in patient matched primary and metastatic tumor pairs, with 5 tumors having ERBB2 alterations exclusive to the primary tumor and 7 ERBB2 alterations exclusive to the metastasis." (PMID 41422272, 2025). "In patients with luminal-like phenotype at diagnosis, the most frequently mutated gene during metastatic disease was PIK3CA (39.8%); in those with HER2+ phenotype, ERBB2 was the most frequently altered gene (30%)." (PMID 38473737, 2024). "Median ERBB2 expression was similar between primary and metastatic tumors (47 v 47 TPM, p = 0.95) but significantly higher in liver metastases (59 v 45 TPM, p < 0.001)." (PMID 38136267, 2023). "A switch from a ERBB2-zero primary tumor to a ERBB2-low metastatic tumor was the most frequent (28.9%)." (PMID 36107428, 2022). "Patients with ERBB2-low MBC had more frequent de novo metastatic disease compared with patients in the ERBB2-zero group (1742 patients [37.3%] vs 2889 patients [27.8%])." (PMID 36107428, 2022).
metastatic disease (continued). "In GB-S6 and GB-S7, ERBB2 amplification was uniformly identified from primary tumors to metastatic tumors." (PMID 36476508, 2022). "De novo metastatic disease was again more frequent in the ERBB2-low group compared with the ERBB2-zero group (1545 patients [37.8%] vs 2316 patients [28.3%])." (PMID 36107428, 2022). "In HNSCC, ERBB2 is upregulated in primary and metastatic tumors, which is related to poor prognosis." (PMID 34459788, 2021). "We note that the ERBB2 amplification was also detected correctly in 10 out of 14 patients using data from matched metastatic tumour sites, and in 7 out of 14 patients using data from primary tumour sites." (PMID 33033274, 2020). "Our results are in line with MYC amplification serving as a poor prognostic marker, of three patients with MYC and ERBB2 co-amplification one suffered from metastatic disease, one from a local recurrence, and one from a localized disease." (PMID 31827209, 2019). "A graph of data from aCGH analysis of the metastatic tumor labeled 13-19 shows a high-level, focused amplification encompassing the entire ERBB2 gene on chromosome 17q12." (PMID 25970776, 2015). "In experimental studies the over-expression of Neu/ErbB-2 protein has been shown to be an important determinant of malignant transformation, development of metastatic disease, and increased cell proliferation." (PMID 22754462, 2012). "Another oncogene, ERBB2, was found overexpressed in PCa with an increasing incidence from localized to metastatic disease." (PMID 19691856, 2009). "The incidence of ERBB2 amplification in metastatic tumours was significantly higher than that in primary tumours." (PMID 2386738, 1990). "However, the HER2DX ERBB2 mRNA score was statistically significantly higher in patients with de novo metastatic disease than those with recurrent disease." (PMID 40280938, 2025). "ERBB2 expression was similar between primary and metastatic tumors (47 v 47 mTPM, p = 0.95)." (PMID 38136267, 2023). "In mice models, knockdown of Bcl3 in ErbB2 positive BC resulted in decreased cell motility and metastatic progression without affecting primary tumor growth; however, resulted in severe reduction of lung metastatic tumors." (PMID 29287594, 2017). "Further intrapatient tumor heterogeneity of these highlighted gene copy number changes was analyzed by fluorescence in situ hybridization (FISH) in all available primary and metastatic tumor biopsies, and ErbB2 protein expression was investigated by immunohistochemistry." (PMID 22014070, 2011). "However, the proportion of de novo metastatic diseases was higher in the ERBB2-low population." (PMID 36107428, 2022). "It is necessary to underline that although mutated ERBB2, PTPRT, PTPRD and AURKB predicted poor OS in univariate analysis they were excluded from the multivariate analysis because they were preferentially identified in patients with late stage (stage III-IV) and/or metastatic disease." (PMID 29844865, 2018). "However, loss of PTEN is involved in the resistance against ErbB2-targeted therapies and depletion of PTEN from ErbB2 positive CSC generates trastuzumab resistant metastatic tumors in immunocompromised mice, anticipating similar problems in the therapy response in human as well." (PMID 24709902, 2014). "There is a growing body of evidence describing tumor biomarker conversion, i.e. upregulation or downregulation of hormone receptors, HER2/ERBB2 and Ki-67/MKI67 when comparing metastatic tumors (MT) with primary tumors (PT)." (PMID 28881657, 2017). "In HER2-positive metastatic disease, GEM also has been used in combination with trastuzumab, a monoclonal antibody that inhibits HER2/neu (ErbB-2) signaling." (PMID 25379013, 2014).
metastatic disease (continued). "Recent attempts of treatment for unresectable or metastatic disease comprise targeted therapies against the epidermal growth factor receptor (EGFR, ErbB1) and the human epidermal growth factor receptor 2 (HER2, ErbB2)." (PMID 22240798, 2012). "Of significance, patient 5 presented with HER2 negative primary and metastatic disease but gain of the region containing ERBB2 was detected in 5/9 cfDNA samples and gain or amplifcation was detected in 5/6 CTCs spanning 3 time points." (PMID 41351070, 2025). "While paired samples from individual CCC patient tumors would provide a more meaningful assessment of enrichment of ERBB2 in peritoneal metastatic tumors, data on copy number variation in such pairs have not been reported and are not publicly available." (PMID 33199705, 2020). "However, only ErbB2 and MET levels were found to be statistically different between samples from primary and metastatic tumor tissue and, along with ErbB3, they exhibited the highest variation of expression values." (PMID 29719603, 2018). "Our data suggest that neither IHC nor ERBB2 gene amplification in the primary tumor play a role in prognosis after diagnosis of metastatic disease." (PMID 25720673, 2015). "ERBB2 amplification was seen in ctDNA in other cases, while not being validated in primary or metastatic tumor tissues." (PMID 26669280, 2015). "Regardless of histological type, amplification of ERBB2 gene was detected in 8 metastatic tumours (25.0%), out of which three tumours had coamplification of HST1 and INT2 genes." (PMID 2386738, 1990). "Furthermore, sWGS analysis revealed gain of the region containing ERBB2 in cfDNA and CTCs, indicating either a switch from HER2-negative metastatic disease or the expansion of a pre-existing subclonal HER2-amplified population, potentially responsible for lack of response to lines of treatment." (PMID 41351070, 2025). "An independent study was carried out to understand at a cellular level why and how most of the ErbB2 positive DCIS do not develop into invasive and metastatic disease." (PMID 24709902, 2014).
invasive ductal carcinoma (608 papers, 2005 to 2026). "ERBB2 gene mutation mainly happens in ERBB2high cancers, such as cervical squamous cell carcinoma, stomach adenocarcinoma, breast invasive ductal carcinoma, uterine corpus endometrioid carcinoma, cholangiocarcinoma, and bladder urothelial carcinoma." (PMID 36172165, 2022). "Luminal (A and B, expressing hormonal receptors) and HER2 (encoded by ERBB2) amplified molecular subtypes of invasive ductal carcinoma are more genetically stable and show less frequent loss of the inactive X chromosome." (PMID 25653311, 2015). "Last, we tested clinical factors (pathologic stage, grade, tumor size (pT), node status (pN), luminal subtype A vs B, progesterone receptor (PR) status, ERBB2 status, Ki‐67 status, and invasive ductal adenocarcinomas vs others, menopause status)." (PMID 37491786, 2023). "Of the 20 patients, the pre-NAC median tumor size on MRI was 3.0 cm (interquartile range, 2.0-5.0 cm); 19 patients (95%) had invasive ductal carcinoma, 15 (75%) had stage II cancer, 11 (55%) had ERBB2-positive cancer, and 6 (30%) had triple-negative cancer." (PMID 33449096, 2021). "For example, ERBB2 (HER2), a well-known proto-oncogene, is overexpressed owing to gene amplification in 25–30% of invasive ductal breast carcinomas." (PMID 26760963, 2016). "Comparative transcriptomics analysis between the EGF-induced, ErbB2 expressing MCF10A cells and a set of ErbB2 expressing invasive ductal carcinoma (IDC) samples identified a shared signature of 361 genes." (PMID 24709902, 2014). "We previously reported a significant inverse correlation between Myc promoter-binding protein-1 (MBP-1) and ERBB2 expression in primary breast invasive ductal carcinoma (IDC)." (PMID 23421821, 2013). "Unlike HER2-amplified tumors in invasive ductal carcinoma (IDC), ILC often harbors ERBB2 mutations instead of amplification." (PMID 39594781, 2024). "Furthermore, cancer epithelial cells protruded along the invasive ductal carcinoma region, corresponding with the expression of ERBB2 as well." (PMID 36456571, 2022). "TCGA-A8-A08S is a triple-positive (for ER, PR and HER2) invasive ductal carcinoma from a 71-year-old woman (top), and its genome showed multiple focally amplified segments in 11q and 17q, encompassing CCND1 and ERBB2, respectively." (PMID 37198482, 2023). "Another study has shown that nuclear BCL9L is associated with high nuclear grade and the expression of ErbB2/HER-2 in both DCIS and invasive ductal carcinoma (IDC)." (PMID 34545187, 2021). "The human epidermal growth factor receptor HER2 (ErbB2, HGNC: 3430) is a well-studied tyrosine kinase (TK) membrane receptor which functions as a therapeutic target in invasive ductal breast carcinomas (IDC)." (PMID 32733648, 2020). "Indeed, it was shown that activation of PPARδ in the mouse mammary epithelium results in the appearance of estrogen receptor- and progesterone receptor-positive and ErbB2-negative infiltrating ductal carcinomas which are associated with an up-regulation of Plac1." (PMID 24304549, 2013). "Gene expression profiling can further classify invasive ductal carcinomas into five subtypes: luminal A, luminal B, ERBB2 (human epidermal growth factor receptor 2, HER2), basal and normal-like." (PMID 20027313, 2009). "In this study, we focused on the outcomes of neoadjuvant treatment for strongly HR-positive and ERBB2-negative invasive ductal carcinoma (IDC) of the breast." (PMID 33710293, 2021). "This cohort study included patients with a diagnosis of invasive ductal carcinoma (IDC) with strong HR positivity and ERBB2 negativity, treated between January 1, 2009, and December 31, 2016, with follow-up from the index date (ie, date of IDC diagnosis) to December 31, 2018." (PMID 33710293, 2021).
invasive ductal carcinoma (continued). "Is neoadjuvant endocrine therapy (NET) an alternative treatment for neoadjuvant chemotherapy (NACT) in patients with invasive ductal carcinoma (IDC) of the breast who have strong hormone receptor (HR) positivity and human epidermal growth factor receptor 2 (ERBB2) negativity?" (PMID 33710293, 2021). "We then applied RFA to high coverage sequence data obtained from a fresh frozen sample of a grade 3, ERBB2 amplified, estrogen receptor (ER) negative invasive ductal carcinoma (IDC)." (PMID 26286554, 2015). "It is important to note that although the “two-hit” theory for ErbB2-induced invasion is well experimentally supported, it is still not known if ErbB2 positive invasive ductal carcinomas develop from ErbB2 positive DCIS." (PMID 24709902, 2014). "Therefore, the ErbB2 oncogene appears to reprogram tumour differentiation so that instead of the histopathologically distinct tumours induced by NCAPH overexpression, the characteristics of infiltrating ductal adenocarcinoma predominated." (PMID 38344872, 2024). "All PBCs were invasive ductal carcinomas, the pathological grade was high (grade 2–3), 29% of tumors were estrogen receptor (ER)-negative, 50% were progesterone receptor (PR)-negative, and 21% were ERBB2-positive." (PMID 31086113, 2019). "We performed in silico comparison of ERBB2 non-amplified cases of ER+ stage I–III primary ILC (N = 279) and invasive ductal carcinoma (IDC, N = 1301) using METABRIC, TCGA, and MSK-IMPACT information." (PMID 32782013, 2020).